MCL1 (MCL1 apoptosis regulator, BCL2 family member)
Diseases named in the same sentence as MCL1 in open-access papers (continued):
Sharing a sentence is not in itself a finding about the gene and the disease.
breast carcinoma (continued). "Mcl-1 is an anti-apoptotic Bcl-2 family member that is often over-expressed in breast tumors and correlates with poor survival in breast cancer patients." (PMID 24971890, 2014). "In breast cancer, the Mcl-1 gene is frequently amplified, allowing for its overexpression despite its short half-life." (PMID 24971890, 2014). "It was further explored that miR-26a increased sensitivity of breast cancer cells to paclitaxel in which MCL-1 was involved." (PMID 23750239, 2013). "MCL-1, an anti-apoptotic member of the Bcl-2 family, as novel targets of miR-26a was found to be in reverse correlation with ectopic expression of miR-26a and knockdown of MCL-1 phenocopied the effect of miR-26a in breast cancer cell lines." (PMID 23750239, 2013). "In order to address the functional role of MCL-1 in breast cancer cells, MDA-MB-231 and MCF-7 cells were transfected with MCL-1-specific siRNAs." (PMID 23750239, 2013). "GSK3β inactivation through AKT hyperactivation was shown to increase anti-apoptotic Mcl-1 protein levels in breast cancer." (PMID 23565238, 2013). "The result showed that the endogenous MCL-1 expression was obviously increased in all 4 breast cancer cell lines." (PMID 23750239, 2013). "In human breast cancer cells, paclitaxel treatment resulted in MCL-1 degradation which was prevented by a proteasome inhibitor, MG132." (PMID 23577147, 2013). "The involvement of SRSF1 in the production of the anti-apoptotic of Mcl-1 in breast cancer cells adds to the number of cancer specific splicing events controlled by this SR protein." (PMID 23284704, 2012). "We recently reported, in particular, that Mcl-1 participates in survival maintenance of breast cancer cells, at the very least in that of the HER2-amplified subtype." (PMID 22703841, 2012). "Knockdown of SRSF1 resulted in a decrease in Mcl-1 in the breast cancer cell lines studied and an increase in the choriocarcinoma cells, and achieved this by both affecting protein stability and translation of Mcl-1." (PMID 23284704, 2012). "Although Mule, an E3 ligase that targets Mcl-1 for degradation was expressed in mammary epithelial and breast cancer cell lines, rapid increase of polyubiquitinated Mcl-1 and Bcl-2 was detected only in mammary epithelial cells." (PMID 21730980, 2011). "We next examined the key players or mechanisms that increased the ubiquitination and degradation of Mcl-1 and Bcl-2 in mammary epithelial cells as well as their aberrations in breast cancer cells." (PMID 21730980, 2011). "Downregulation of pERK1/2 by treatment with MEK inhibitor or nitric oxide donor also increased Mule–Mcl-1 complex and caspase-3 activity in breast cancer cells, indicating induction of apoptosis." (PMID 21730980, 2011). "While breast cancer cells were resistant to de novo inhibition of protein synthesis, a rapid proteosome-mediated degradation of Mcl-1 and Bcl-2 induced apoptosis in mammary epithelial cells." (PMID 21730980, 2011). "Since ubiquitination of Mcl-1 was reduced in breast cancer cells even though Mule was constitutively expressed or induced by CHX, we examined the association of Mcl-1 and Mule by immunoprecipitation assays." (PMID 21730980, 2011). "Most breast cancers arise from epithelial cells that express Bcl-2, Bcl-xL and Mcl-1, and enhanced expression of these proteins is almost systematically found in transformed mammary epithelial cells." (PMID 21899728, 2011). "Downregulation of pERK1/2 in breast cancer cells reduced Mcl-1 levels and increased Mcl-1/Mule complex." (PMID 21730980, 2011). "We did find downregulating HRF in breast cancer cells increased Mcl-1 ubiquitination and apoptosis; however, higher apoptosis induction was observed when Mcl-1 was directly downregulated by Mcl-1 siRNA or indirectly by downregulating pERK1/2." (PMID 21730980, 2011).
breast carcinoma (continued). "We show that downregulation of Mcl-1 by Mcl-1 siRNA or inhibiting ERK1/2 through U0126 or nitric oxide treatment increased the sensitivity of breast cancer cells to CHX-induced apoptosis." (PMID 21730980, 2011). "It is possible that additional mechanisms operate in breast cancer cells that increase stability of Mcl-1 and resistance to apoptosis." (PMID 21730980, 2011). "Our findings suggest that reduced Mule/Mcl-1 complex has a significant role in increasing the stability of Mcl-1 in breast cancer cells and increased resistance to apoptosis." (PMID 21730980, 2011). "The HER2 amplified BT474 breast cancer express detectable levels of the main anti-apoptotic Bcl-2 homologues Bcl-xL, Bcl-2 and Mcl-1." (PMID 21899728, 2011). "We show that the depletion of Mcl-1 is sufficient to induce apoptosis in HER2-overexpressing breast cancer cells." (PMID 21899728, 2011). "In this study, we found that increased stability of anti-apoptotic proteins like Mcl-1 and Bcl-2 rendered breast cancer cells resistant to CHX-induced apoptosis." (PMID 21730980, 2011). "In breast cancer cells, reduced ubiquitination and degradation of Mcl-1 and Bcl-2 was detected with CHX treatment." (PMID 21730980, 2011). "Our finding of increased stability of Mcl-1 in breast cancer cells due to reduction of Mcl-1–Mule complex introduces new players that can be targeted for therapeutic interventions to induce apoptosis in breast cancer." (PMID 21730980, 2011). "Accordingly, we initially examined the stability of Mcl-1 associating proteins in CHX-treated mammary epithelial and breast cancer cells." (PMID 21730980, 2011). "We examined the expression of Mule, the specific E3 ligase for Mcl-1 by western blot analysis in both the normal mammary epithelial and breast cancer cells." (PMID 21730980, 2011). "Our investigation of published expression data hint on a selective enrichment for Mcl-1 trancripts in HER2 amplified mammary tumors compared to other mammary tumors." (PMID 21899728, 2011). "In addition to hematological cancers, some solid tumors, such as breast cancer, melanoma, and pancreatic ductal adenocarcinoma, were also reported to be reliant on MCL1 for survival." (PMID 40075071, 2025). "Given the growing interest in developing MCL1-targeted therapies for cancers, such as acute myeloid leukemia and breast cancer, RPS4X could represent an upstream regulatory factor worth targeting to overcome apoptotic resistance." (PMID 41154579, 2025). "Moreover, we have demonstrated that MOXI can increase the level of Mcl-1 protein in MDA-MB-231 breast cancer cells." (PMID 40892149, 2025). "Furthermore, the role of Bcl-2 and Mcl-1 is not limited to apoptosis; they play a vital role in cell cycle progression, especially in breast cancer." (PMID 39407625, 2024). "Given the frequency of MCL1 copy number variations in breast cancer, we asked whether there were transcriptional differences between MCL1-amplified versus wildtype lesions." (PMID 38523186, 2024). "We are unaware of prior data on MCL1 in preinvasive human breast cancer." (PMID 38523186, 2024). "Furthermore, we validated that treatment with GA led to a significant reduction in TRX and MCL1 expressions in 4T1 breast cancer cells, resulting in highly efficient killing effect (IC50 = 2.20 μg mL−1) against 4T1 cells." (PMID 38342612, 2024). "Moxifloxacin (another quinolone) can contribute to S-phase arrest and the induction of apoptosis by cisplatin in pancreatic cancer through ERK activation, inhibit tumor growth or promote apoptosis in breast cancer by interacting with the Mcl-1 and MITF proteins." (PMID 38926655, 2024). "Moreover, findings from human breast cancer study using the MMTV-PyMT mouse model highlighted the crucial role of MCL-1 in early tumor development and progression." (PMID 39012900, 2024).
breast carcinoma (continued). "Interestingly, MCL-1 amplifications are more frequent in breast cancer compared to colorectal or ovarian cancer which will ultimately nullify the impact of TRIP12 inhibition in those cells." (PMID 36672454, 2023). "Mcl-1 overexpression is found in many cancers, including breast cancer." (PMID 37896184, 2023). "Thus, our data highlight the importance of stratifying breast cancer patients on their MCL-1 expression for Taxol therapy as previously suggested." (PMID 36672454, 2023). "Mcl-1 nioplexes were combined with TZ for dual therapy in HER2-overexpressing breast cancer cells." (PMID 37896184, 2023). "According to these results, we hypothesized that JNK and ERK/MAPK signaling pathways might account for ROS-mediated MCL-1 downregulation and apoptosis promotion in ER+ breast cancer cells." (PMID 37352173, 2023). "Interestingly, a further study showed Mcl-1 and Bcl-xL protein and mRNA levels were reduced in KLF4/KLF5-deficient breast cancer cells." (PMID 37686541, 2023). "Mcl-1 was shown to have high levels of expression in untreated breast cancer cell lines." (PMID 37736508, 2023). "A previous study demonstrated that EGF could promote breast cancer cell survival by regulating the expression of anti-apoptotic factor Mcl1 through the MAPK-Elk1 signaling pathway." (PMID 36770773, 2023). "However, elevated MCL-1 expression makes ER+ breast cancer cells resistant to venetoclax and weakens the therapeutic effect of this drug." (PMID 37352173, 2023). "This is in line with the analysis of breast cancer cell lines in Cancer Cell Line Encyclopedia data, which highlights a role for both MCL1 and BCL2L1 (BCL-XL) in maintenance of breast cancer cell line viability in 2-D culture, whereas BCL2 appears largely non-essential in this context." (PMID 35349392, 2022). "In various examples of human cancer lines such as prostate cancer, myeloid leukemia, breast cancer, glioblastoma etc., it has been demonstrated that they have heighten expression of multiple anti-apoptotic Bcl-2 proteins (Bcl-2, Bcl-XL and Mcl-1) and have displayed strong chemo resistance." (PMID 36267274, 2022). "However, it has been discovered that 14-deoxy-11, 12-didehydroandrographolide increases the expression of anti-apoptotic Mcl-1 mRNA by 2.29-fold in the T-47D (human breast carcinoma) cell line." (PMID 35745769, 2022). "MCL-1 protein abundance is the product of a series of upstream events, which may also be perturbed in breast cancer, such that quantification of MCL1 gene and mRNA copy number levels may underestimate the extent to which MCL-1 is upregulated." (PMID 35349392, 2022). "Furthermore, curcumin can trigger TNFRSF10A-induced apoptosis in TNFRSF10A-resistant breast cancer cell lines via regulating apoptosis-related proteins such as MCL1, MAPK/ERK and AKT and genes such as MCL1." (PMID 36497321, 2022). "Scientific data have revealed the elevated level of Mcl-1 protein expression in breast cancer." (PMID 36045272, 2022). "Indeed, studies utilizing breast cancer cell lines first indicated a requirement for MCL-1 to maintain cell viability, as genetic knock-down of MCL1 induces cell death in a subset of both TNBC and ER-positive breast cancer cell lines grown in 2-D monolayer." (PMID 35349392, 2022). "One of these mechanisms is based on over expression of various genes involved in anti-apoptosis processes, including members of the Bcl-2 family such as BCl 2, Bcl-XL, BCL-W, and MCl-1 which are elevated in a variety of cancers, including breast cancer and inhibit cell death in tumors." (PMID 35725497, 2022). "We demonstrated that deletion or pharmacological inhibition of MCL-1 with either S63845 or A1210477 BH3-mimetics impaired the tumorsphere-forming capacity of breast cancer cells, and that genetic ablation of pro-apoptotic effector proteins BAX and BAK abrogates this effect." (PMID 35349392, 2022).
breast carcinoma (continued). "Moreover, research suggests that Mcl-1 and Bcl-xL act redundantly in breast cancer cell survival, as the ratio of Mcl-1 to Bcl-xL was necessary for cell viability." (PMID 35053443, 2022). "Other Bcl-2 family proteins co-expressed alongside Bcl-2 in ER+ breast cancer include Mcl-1." (PMID 35053443, 2022). "Notably, high levels of MCL-1 occur in breast cancer, where functional dependency has been demonstrated using cell lines and mouse models." (PMID 35349392, 2022). "This suggests that, in tumor cells with high Mcl-1 dependency, a rationally devised combination treatment targeting Mcl-1, as well as single-agent Mcl-1 inhibitors, may trigger cell death in breast cancer." (PMID 35745769, 2022). "Moreover, recent evidence from in vitro experiments suggests a significant role for Mcl-1 in breast cancer cell survival, particularly in triple-negative breast cancers." (PMID 36045272, 2022). "Furthermore, resistance to targeted therapies in HER-2 amplified breast cancer can be conferred by microRNA-4728-mediated suppression of NOXA which serves to prevent apoptosis of breast cancer cells in an MCL-1 dependent manner." (PMID 35349392, 2022). "Moreover, this research investigated how 3nAGN-NSC affected Mcl-1 expression and if suppressing Mcl-1 mRNA by siRNA to a particular target makes MCF-7 breast cancer cells more susceptible to 3nAG therapy via the apoptotic pathway induction." (PMID 35745769, 2022). "When focused on specific indications, MDM2 could be used with MCL1 inhibitors in breast cancer and lung adenocarcinoma." (PMID 35249548, 2022). "Furthermore, GSK-3 protein expression is inversely correlated with MCL1 expression in primary breast cancer patient tissue, and increased levels of MCL-1 protein in this patient cohort are associated with worse prognosis." (PMID 35349392, 2022). "Taken together, these findings suggest that the most potent effects of MCL-1 inhibition in breast cancer may occur when used in combination with additional therapies that drive an increasingly “primed” apoptotic state." (PMID 35349392, 2022). "Interestingly, for the anti-apoptosis proteins, a genetic alteration of Mcl-1, involving its amplification, is more common in breast cancer development than Bcl-2 and Bcl-xL amplification in clinical breast cancer datasets and is linked to a worse outcome." (PMID 35745769, 2022). "Our study thus brings support to the notion that MCL-1 targeting may improve the treatment of breast cancer while putting forth an effect not only on cancer cells but also on non-malignant cells that interact with them." (PMID 36104324, 2022). "Whilst preclinical work has validated MCL-1 as a relevant target in breast cancer, the essentiality of MCL-1 in many normal cell types may necessitate careful administration of MCL-1 targeting drugs to facilitate a therapeutic window." (PMID 35349392, 2022). "Both loss-of-function mutations and promoter hypermethylation of the E3 ubiquitin ligase FBW7 have been identified in breast tumors suggesting that the extent of MCL-1 protein upregulation in breast cancer may be as yet underappreciated." (PMID 35349392, 2022). "Following the literature review, the current study is the first that determines the role of MITF and Mcl-1 proteins in the MFLX-induced cellular and molecular cascade underlying the drug’s cytotoxic and pro-apoptotic effect on triple-negative MDA-MB-231 breast cancer cells." (PMID 36045272, 2022). "They found that the constructed PBP@Cas13a/crMcl-1 nanosystem may suppress Mcl-1 at the transcriptional level, lowering Mcl-1 protein expression and increasing apoptosis in breast cancer cells through in vitro and in vivo tests." (PMID 36421127, 2022). "Furthermore, the correlation between MCL-1 overexpression and stem cell-like potential has been reported previously in several cancer types, such as breast cancer, leukemia, lung cancer, and glioblastoma." (PMID 35136016, 2022).
breast carcinoma (continued). "Interestingly, we find that MCL-1 is also critical for stem cell activity in human breast cancer cells and high MCL1 expression correlates with stemness markers in tumours." (PMID 33785871, 2021). "Furthermore, reduction in BAX/BAK ablated the negative impact of both genetic and pharmaceutical targeting of MCL-1 in breast cancer stem cells." (PMID 33785871, 2021). "Indeed, increasing evidence suggests that Mcl-1 is important in melanoma, hepatocellular carcinoma, breast cancer, and various hematological malignancies." (PMID 34336857, 2021). "As with single-agent BCL-XL inhibition, MCL-1 inhibitors used as monotherapy are only marginally effective in solid tumour-derived cell lines such as patient-derived xenograft (PDX) models of breast cancer and KRAS-mutant NSCLC." (PMID 34581776, 2021). "Thus, at appropriate dosing regimens, pharmaceutical targeting of MCL-1 with BH3-mimetics such as S63845 can act as a single-agent therapy to slow tumour growth in a syngeneic mouse model of breast cancer." (PMID 33785871, 2021). "We therefore wished to further model targeting MCL-1 in a breast cancer therapy setting and test whether inhibition of MCL-1 with a BH3-mimetic drug would impact on clinically palpable mammary tumours." (PMID 33785871, 2021). "In this study, we aimed to explore whether dinaciclib was sufficient to sensitize preclinical models of HER2-amplified breast cancer through downregulation of MCL-1." (PMID 33589591, 2021). "Indeed, we found that the anti-apoptotic proteins BCL-xL and MCL-1 are crucial for ER+ breast cancer cells resistance to therapy, as they exert a dual inhibition of the pro-apoptotic protein BIM and compensate for each other." (PMID 34359829, 2021). "Mcl-1 is also a vital protein regulating breast cancer cell survival." (PMID 33919902, 2021). "Downregulation of USP9X reinforces cisplatin sensitivity in ER- breast cancer cells, which is speculated to be a result of the degradation of MCL1." (PMID 34575114, 2021). "Together, the combination therapy between Mcl-1 silencing and Dox exhibits a synergistic effect that may be exploited for novel breast cancer treatment." (PMID 33919902, 2021). "Moreover, it was found that Mcl-1 was highly expressed in tumor lesions in a genetic mouse model of breast cancer, MMTV-PyMT." (PMID 34336857, 2021). "An important role for MCL-1 in breast cancer stem cells has been suggested and we reasoned that the bulk of cells growing in vitro in monolayers might not represent the cells driving tumour maintenance in vivo such as cancer stem cells." (PMID 33785871, 2021). "Other aspects of drug resistance were also derived from the stress protein Bcl-2-associated athanogene 3 (BAG3), which could stabilize Mcl1 expression, thus contributing to ABT-737 resistance in breast cancer and prostate cells." (PMID 34753495, 2021). "Furthermore, the high cytotoxicity showed by the BH3 mimetic S63845 reinforces the idea that one of the key anti-apoptotic proteins in breast cancer is MCL-1." (PMID 34359829, 2021). "In addition to its prominent role in haematopoietic cancers, MCL-1 has emerged as a key player in breast cancer with high levels of MCL-1 protein in primary breast cancer samples correlating with poor patient prognosis." (PMID 33785871, 2021). "Together, these data suggest that MCL-1 may be an important player in maintaining stem cell populations of primary breast cancers." (PMID 33785871, 2021). "MDA-MB-231 control cells were highly sensitive to MCL-1 inhibition with S63845 in the tumoursphere assay and MCL1-deficient cells were unable to form tumourspheres in vitro confirming a specific role for MCL-1 in breast cancer stem cell function." (PMID 33785871, 2021).